MYC (MYC proto-oncogene, bHLH transcription factor)
Diseases named in the same sentence as MYC in open-access papers (continued):
Sharing a sentence is not in itself a finding about the gene and the disease.
breast cancer (continued). "Additionally, the c-MYC-regulated miR-23a ~ 27a ~ 24-2 cluster promotes cell invasion and hepatic metastasis of breast cancer by targeting SPRY2." (PMID 39112518, 2024). "Notably, MYC can enhance oxidative phosphorylation to promote chemotherapy resistance in breast cancer." (PMID 39867911, 2024). "Up-regulation of MYC and of other breast cancer-related genes in malignant C1 cells speculatively suggests functionality of these de novo interactions." (PMID 38076897, 2024). "The proteasome degradation pathway of c-MYC, a frequently overexpressed oncogene in breast cancer, may also depend on SUMOylation; its SUMOylation at K326 results in its subsequent ubiquitylation and degradation by the proteasome." (PMID 39127633, 2024). "Additionally, circACTN4, potentially mediated by USF2, interacts with FUBP1 to facilitate breast cancer progression by upregulating MYC expression." (PMID 39430741, 2024). "In addition, Etomoxir, the most commonly used CPT1 inhibitor, had a significant inhibitory effect on MYC-induced mammary carcinoma mice." (PMID 39027328, 2024). "The aim of this study was to investigate the inhibitory effect of miR-561-3p on ZEB1, HIF1A, and MYC expression as oncogenes that have the most impact on PD-L1 overexpression and cellular processes such as proliferation, apoptosis, and cell cycle in breast cancer (BC) cell lines." (PMID 38462658, 2024). "FGF13-AS1 has been found to play a predominantly oncogenic role in breast cancer, reducing the glycolytic and stemness properties of breast cancer cells by inhibiting MYC expression through binding to insulin-like growth factor 2 mRNA-binding proteins (IGF2BPs)." (PMID 37204526, 2023). "We identified the AP4 gene as a direct target of c-MYC in the breast cancer cell line MCF-7." (PMID 36831504, 2023). "Namely, c-MYC regulates expression of AHCY in human breast cancer cells." (PMID 38003292, 2023). "In addition to the promoting effect of CAFs on breast cancer, some studies have also shown that CAFs slow down breast cancer growth by downregulating c-MYC." (PMID 36721232, 2023). "OGT expression has been shown to be upregulated by c-MYC in breast cancer cells." (PMID 37152043, 2023). "In addition, FTH1 exerts significant antigrowth effects in breast cancer cells by inhibiting the expression of c-MYC." (PMID 38069262, 2023). "Copy number aberrations (CNAs) of MYC are frequent in breast cancer." (PMID 37704631, 2023). "Expression of OCT4 and MYC present an interesting avenue of investigation, particularly in basal breast cancer subtypes and may yield interesting insights into the mechanisms regulating reoviral selectivity in breast cancers." (PMID 37515162, 2023). "Here, we show that MYC activation drives resistance to mTOR inhibitors (mTORi) in breast cancer." (PMID 37642941, 2023). "In addition, upregulated CCND2, SNHG16, MYC, and GNAS levels were associated with accelerating cell cycle progression, as well as promoting growth and metastasis in lung cancer, breast cancer, and colon cancer." (PMID 37007962, 2023). "MYC, an oncogene, is significantly amplified and highly expressed in breast cancer." (PMID 36782197, 2023). "Finally, we overexpressed human MYC in the human breast cancer cell lines SUM52PE, MDA-MB-468, MCF7, and T47D." (PMID 37642941, 2023). "Let-7 contributes to the regulation of several signaling pathways, such as breast cancer cell growth, the regulation of MYC expression, and the regulation of CSC properties, and could be a potential therapeutic target for breast cancer patients." (PMID 37759508, 2023). "LAPTM4B gene localized in chromosome 8q.22.1, a region containing the MYC oncogene and is amplified in breast cancer and prostate cancer, which prompted us to investigate whether the LAPTM4B copy number is increased in OS." (PMID 37147294, 2023).
breast cancer (continued). "In addition to GC development being regulated by c-Myc, it also takes place in breast cancer cell proliferation as it suppresses apoptosis via upregulating the genes cyclin D1 and c-MYC with the help of the STAT3 pathway." (PMID 37514090, 2023). "On the other hand, it was observed that in breast cancer, miR-616 could inhibit tumor cell growth and migration by suppressing c-MYC expression, demonstrating a tumor suppressor role." (PMID 38002073, 2023). "In breast cancer cells, targeting c-MYC has been demonstrated to inhibit tumor angiogenesis." (PMID 36721232, 2023). "In addition to breast cancer, MYC expression is increased in many other human cancers, both through gene transcription and protein stability." (PMID 37047814, 2023). "Similarly, AZD4547 has been shown to inhibit stemness features in the BT-474 breast cancer cell line, including MYC gene expression, providing additional rationale for using AZD4547 to avoid VM formation." (PMID 37762073, 2023). "Similarly to MYC, high expression levels of PVT1 have been associated with a poor prognosis in breast cancer and other human malignancies." (PMID 36901971, 2023). "Furthermore, disruption of the PVT1 promoter by CRISPR can enhance breast cancer cell competition promoted by MYC." (PMID 36624542, 2023). "Therefore, the intercommunication between breast cancer cells and TAM upregulates c-MYC expression, accelerating the breast cancer progression." (PMID 36721232, 2023). "Comparative genomics between the MMTV-Myc histological subtypes and MYC-driven human breast cancers may be an important area of future study." (PMID 37805590, 2023). "Previous reports have established that WT1 might activate MYC transcription in breast cancer and lung cancer cells." (PMID 37667197, 2023). "Treatment with pterostilbene simultaneously reduced the expression levels of c-MYC and hTERT in breast cancer cells, indicating that pterostilbene may downregulate hTERT expression in these cells by inhibiting c-MYC." (PMID 37612721, 2023). "However, we can’t exclude that MYC still contributes to the partial-EMT phenotype seen in the majority of the basal-like breast cancers." (PMID 38111531, 2023). "Overall, these results suggest that METTL3 may indirectly regulate AS in breast cancer via m6A deposition in MYC mRNA." (PMID 36725888, 2023). "Kaplan–Meier analysis on breast cancer patients revealed MYC amplification was present in 18.2% of patients surveyed, with median overall survival at 135.2 months (95% CI: 113.7–148.1) compared to the unaltered population with median overall survival at 171.3 months (95% CI: 161.2–182.9)." (PMID 37805590, 2023). "Moreover, DNA damaging agents (e.g., topoisomerase II inhibitors) or ionizing radiation induced DNA damage as well as c-MYC inhibition in MCF-7 breast cancer cells." (PMID 37627164, 2023). "An independent dataset derived from 30 human breast cancer cell lines validated the negative association between MYC amplification and mTORi response." (PMID 37642941, 2023). "Furthermore, the PVT1 promoter, located only 55 kb away from the MYC promoter, functions as an onco-suppressor in breast cancer independently of the oncogenic PVT1 lncRNA." (PMID 37443779, 2023). "MYC is remarkably elevated in TNBC compared with other breast cancer subtypes." (PMID 37570631, 2023). "Breast cancer cells with higher MYC expression are more stem-like, which is regulated by MAPK/ERK." (PMID 36624542, 2023). "Thus, the function of MYC in the breast cancer secretome in miRNA-high breast tumor cells requires further investigation." (PMID 37128318, 2023). "Our initial hypothesis postulated that the MMTV-Myc model would enrich for claudin-low and basal-like tumors, similar to how human breast cancer patients with amplified MYC are preferentially basal-like or claudin-low." (PMID 37805590, 2023).
breast cancer (continued). "MAF1 and MYC protein expression decreased in HER2-positive breast cancer." (PMID 37801436, 2023). "Moreover, the secretion of CAFs contributes to the expression of c-MYC in breast cancer cells, thereby promoting tumor growth." (PMID 36721232, 2023). "In addition, crosstalk between ER and HER2 has also been shown to upregulate MYC-mediated glutamine metabolism, thus promoting cell proliferation and leading to aromatase inhibitor (AI)-resistant breast cancer cells." (PMID 37258523, 2023). "Finally, the hypoxia-induced increase in KB-1980E6.3 lncRNA expression in breast cancer contributes to the higher stability of MYC mRNA via IGF2BP1 recruitment." (PMID 37443779, 2023). "c-MYC expression is known to be up-regulated in several breast cancers." (PMID 37095445, 2023). "The enrichment with both MYC- and E2F-target genes in the basal-like breast cancers with a partial-EMT phenotype, might indicate that these cancers are highly proliferative and potentially more aggressive." (PMID 38111531, 2023). "p62 expression is elevated in breast cancer stem cells by MYC mRNA stabilization." (PMID 36831455, 2023). "One study found that USP28 could affect the cell cycle and proliferation by regulating MYC abundance in colon and breast carcinomas." (PMID 37450415, 2023). "Therefore, the overexpression of c-MYC, which can enhance these signallings, can thus contribute to the development of tamoxifen resistance in breast cancer." (PMID 35267559, 2022). "Likewise, high expression of the MYC protein or a MYC‐dependent gene signature predicted poor prognosis in patients suffering from estrogen receptor‐positive breast cancer treated with adjuvant hormonal therapy." (PMID 36214609, 2022). "Considering that MYC is highly expressed in some cancers, such as breast cancer and neuroblastoma, the search for inhibitors of mitochondrial fusion opens a new approach for these types of cancer as MYLS22 (OPA1 inhibitor) recently reported by Scorrano’s group." (PMID 35565283, 2022). "MYC-induced expulsion of TILs could explain the ineffectiveness of ICI therapy in a large fraction of triple-negative and BRCA-mutated breast cancers that are potentially immunogenic due to their genomic instability." (PMID 36323660, 2022). "Hence, it cannot be inferred from this data if E2F, MYC or both are involved in the transcriptional regulation of pri-miR-183 – and thereby consistently of all three 5’isomiRs – in breast cancer patients." (PMID 35655310, 2022). "Antitumor effects on MYC-overexpressing breast cancer and neuroblastoma in preclinical models." (PMID 36358940, 2022). "This suggests that overexpression of c-MYC in breast cancer can activate EGFR signalling." (PMID 35267559, 2022). "Indeed, the effects of MYC mainly occur in more aggressive intrinsic subtypes of breast cancer, such as the luminal B, HER2 +, and TNBC forms." (PMID 35053485, 2022). "Although the complete molecular mechanism for endocrine resistance remains to be unraveled, emerging data suggest that c-MYC overexpression may contribute to acquired resistance in ER+ve breast cancers." (PMID 35267559, 2022). "Since ribosomes play an essential role in c-MYC-mediated cancer development, suppressing ribosome biogenesis may help reduce aggressiveness and reverse tamoxifen resistance in breast cancer." (PMID 35267559, 2022). "Finally, we queried the METABRIC breast cancer patient data to examine the correlation between MYC, ZNF148, and ID1/3 expression levels." (PMID 36207293, 2022).
breast cancer (continued). "A large number of studies have indicated that BET inhibitors may be beneficial in the treatment of hematological malignancies and solid tumours including breast cancer, possibly by inhibiting certain key proto-oncogenes such as MYC." (PMID 36525288, 2022). "c-MYC is an essential regulator of glutamine and glucose metabolism and appears to affect a broad spectrum of genes that coordinate energy metabolism and biomass accumulation in preparation for DNA replication and cell division in breast cancer." (PMID 35267559, 2022). "MYC is one of the most highly amplified oncogenes, whose deregulation is commonly found on the path to cancer, including myeloma, head and neck tumors, lymphoma, and breast cancer." (PMID 35591851, 2022). "For instance, LncRNA HOTAIR could lead to the transcriptional activation of c-MYC target genes in breast cancer cells, thus promoting the occurrence of breast cancer." (PMID 35371316, 2022). "Because the prior experiments suggested that the E-box was repressed in the epithelial state, we predicted from the expression patterns that MYC may repress ABCA1 in epithelial breast cancer cells." (PMID 35327383, 2022). "Knockdown of the Timeless gene was able to reduce the tumorigenicity of breast cancer cells in vivo, which may involve the well-known oncogene MYC." (PMID 36359523, 2022). "Using these chemicals might help reverse tamoxifen resistance in ER+ve breast cancer, provided that c-MYC-mediated ribosome biogenesis is the crucial factor for tamoxifen resistance." (PMID 35267559, 2022). "Furthermore, FGF was shown to activate MYC expression directly through activated Akt/Erk signaling in a human breast cancer cell line." (PMID 36555426, 2022). "A high level of MYC drives stemness and an aggressive phenotype in breast cancer." (PMID 36207293, 2022). "Additionally, mRNA splicing is thought to be the rate-limiting step in generating functional transcripts and has been proposed as a potential therapeutic vulnerability in MYC driven breast cancer and lymphoma." (PMID 35589755, 2022). "The induction of the c-MYC gene by E2 is essential for breast cancer cell proliferation." (PMID 35468719, 2022). "MYCMI-7 induces apoptosis in a MYC-dependent manner in tumor cells but not in normal cells at single-digit micromolar concentrations and exhibits potent tumor growth–inhibitory activity in vivo in mouse models of MYC-driven leukemia, breast cancer, and neuroblastoma." (PMID 36874405, 2022). "Furthermore, overexpression of USP22 stimulates breast cancer cell proliferation and aggregation and increases c-MYC tumorigenic activity." (PMID 35935969, 2022). "The SUMO-activating enzyme subunit 1⁄2 (SAE1/SAE2) may promote metastasis in MYC-driven breast cancer, and the SUMO-conjugating E2 enzyme UBC9 has also been shown to advance metastasis in breast cancer." (PMID 35408841, 2022). "For instance, a decrease in PI3K/AKT/mTOR system activity by CTDs blocks the activation of crucial oncogenic molecules, i.e., MYC, which are inhibited in almost 50% of human cancers, including head and neck cancer, small-cell lung cancer, neuroblastoma, and breast cancer." (PMID 35276890, 2022). "c-MYC alteration has been reported in 9.92% of breast carcinoma patients." (PMID 35267559, 2022).
breast cancer (continued). "Taken together, our study identified a novel and potential therapeutic strategy by combined inhibition of BRD4-RAC1 signaling to suppress breast cancer development and tumorigenesis via c-MYC/G9a/FTH1 axis and down regulation of HDCA1 in different molecular subtypes in a context-dependent manner." (PMID 34803511, 2021). "A study has shown that exosomes downregulate the expression of c-MYC in breast cancer cells, but whether exosomes can affect glutamine metabolism of OA chondrocytes by downregulating c-MYC is unknown." (PMID 34992497, 2021). "Increasing researches have suggested that the proto-oncogene MYC might have a vital function in aggressive breast cancers." (PMID 33541412, 2021). "c-MYC and MXI1 proteins may selectively bind the A-allele in breast cancer, although this study utilized two genetically distinct cell lines rather than isogenic lines." (PMID 33918978, 2021). "Since we showed that MYC is a central regulator of fibroblast rewiring during metastatic progression in mice, we asked whether MYC is similarly upregulated in the stromal compartment of human breast cancer." (PMID 34169837, 2021). "Overexpression of MYC might induce the ability of self-renewal and multidirectional differentiation in breast cancer stem cells." (PMID 34362383, 2021). "Knockdown or overexpression of ETV4 significantly restrains or fosters breast cancer cell stem-like traits, and ETV4 loss suppresses the expression of stemness markers including c-MYC, OCT4, NANOG, LIN28, suggesting that ETV4 acts as a key regulator in BCSC maintenance." (PMID 34052833, 2021). "Encouraged by these findings, we next asked whether stromal activation of MYC and its downstream targets is operative in human breast cancer." (PMID 34169837, 2021). "Additionally, in breast cancer cells resistant to the estrogen agonist tamoxifen, as well as to doxorubicin and paclitaxel, increased expression of the proto-oncogene MYC has been found." (PMID 34440124, 2021). "Basal-like breast cancers have increased altered cell cycle checkpoint regulation, DNA damage repair, MYC, and immune response signaling, while proteins associated with recurrent copy number alterations in HGSOC converge on cell migration/invasion and immune regulation pathways." (PMID 33669749, 2021). "Further mechanistic research revealed that circACTN4 could competitively bind to FUBP1 and block the binding of FUBP1 with FIR, thus promoting the transcription of MYC and development of breast cancer." (PMID 34116677, 2021). "Finally, to validate our findings in human metastasis, we analyzed the expression of MYC in a cohort of breast cancer patients with lung metastasis." (PMID 34169837, 2021). "Notably, it has been reported that MYC is preferentially overexpressed in high-grade breast cancer, especially in TNBC, and increased MYC activity is associated with poor outcome." (PMID 33541412, 2021). "Expression of MYC pathway can vary among different molecular subtypes of breast cancer." (PMID 33807872, 2021). "Gene amplification is the most frequent genetic alteration in breast cancer with MYC, CCND1, epidermal growth factor receptor (EGFR), fibroblast growth factor receptor (FGFR), CDK4, and MDM2 being the genes most frequently amplified in primary and recurrent breast tumors." (PMID 33996588, 2021). "Our findings uncover a pivotal mechanism that circACTN4 mediated by USF2 might interact with FUBP1 to promote the occurrence and development of breast cancer via enhancing the expression of MYC." (PMID 34116677, 2021). "The Warburg phenotype in breast cancer has been associated with basal-like, MYC-driven, hormone receptor negative cell lines and tumors." (PMID 34649623, 2021). "Timeless boosts the progression of breast cancer through activating MYC." (PMID 33971927, 2021).